PRMT5 (protein arginine methyltransferase 5)
Diseases named in the same sentence as PRMT5 in open-access papers (continued):
Sharing a sentence is not in itself a finding about the gene and the disease.
cancer (continued). "Knockdown of PRMT5 in various cancer cells can suppress the protumorigenic functions of PRMT543–46." (PMID 36720900, 2023). "In fact, PRMT5 currently is viewed as a hot therapeutic target in cancer." (PMID 38203325, 2023). "Our current understanding of the downstream effects of PRMT5 inhibition include the impairment of pre-mRNA splicing and DNA damage repair, co-treatment of cancers with agents that target these pathways such as PARP inhibitors and chemotherapy, is potentially synergistic." (PMID 37795443, 2023). "Because PRMT5 and APE1 functions in the different DNA repair pathways, simultaneous up- or down-regulation of PRMT5 and APE1 may significantly affect the IR susceptibility of cancer cells." (PMID 37887269, 2023). "Hence, PRMT5 has shown specific epigenetic control of a range of cancer-relevant genes and promotes growth and progression." (PMID 37795443, 2023). "Through these functions, PRMT5 can support cancer cell immune evasion." (PMID 36980950, 2023). "Therefore PRMT5-mediated suppression of antigen presentation also supports immune evasion in cancer." (PMID 36980950, 2023). "This study, though not focusing on RB-deficient cancers, provided important insights as to the mechanism of how PRMT5 regulates cell cycle progression." (PMID 37502925, 2023). "Interestingly, PRMT5 also directly regulates the activity of TIP60 through the dimethylation of RUVBL1, implying that the role of PRMT5 in HR repair in cancer cells is multifactorial." (PMID 36980782, 2023). "Additionally, the enhanced proliferation induced by overexpression of G3BP2-WT was blocked when the absence of PRMT5, suggesting that the methylation of G3BP2 is involved in the event of PRMT5 promotes carcinoma cell growth." (PMID 36878903, 2023). "It led to the development of a different class of substrate-competitive inhibitors that preferentially bind the PRMT5:MEP50 complex with MTA and may be used to pharmacologically exploit the PRMT5-related vulnerability in MTAP−/− cancer cells." (PMID 36192627, 2022). "Chemical targeting of PRMT5 requires further endeavors in the medicinal chemistry field for improved potency, selectivity, efficacy, and other key pharmacologic attributes to serve the need of both basic biology and cancer drug discovery." (PMID 35744905, 2022). "Recently, the role of PRMT5 in cancer development has received significant attention." (PMID 35531958, 2022). "PRMT5 inhibitors have a strong therapeutic potential, as phase I clinical trials in hematological malignancies that use these molecules show promising results, thus, underlining PRMT inhibitors as useful therapeutic tools for cancer treatment in the future." (PMID 36358861, 2022). "In contrast, in cervical cancer, PRMT5 promotes cancer progression by increasing the expression of histone H3R2 symmetric dimethylation (H3R2me2s), which is enriched in the promoter region of STAT1 to enhance transcription and drive up-regulation of PD-L1 expression." (PMID 36713412, 2022). "Therefore, while the mechanism by which PP2A regulates PRMT5 is the similar, the biological outcome of this signaling is contradictory between these two cancers and supports the use of alternative therapeutic approaches." (PMID 35118387, 2022). "PRMT5 inhibitors have shown great promise in clinical trials as a cancer therapy." (PMID 36364261, 2022). "PRMT5 expression in BC was correlated with poor prognosis and manipulating its expression could affect cancer cell growth." (PMID 36199122, 2022). "Previous in vitro studies from various cancer cell lines, however, suggest that PRMT5 could promote the activation of Wnt/β-catenin signaling 17, 64-69." (PMID 35864961, 2022). "NLRC5 expression was inversely correlated with PRMT5 expression in cancer cells." (PMID 35493527, 2022). "A better understanding of the PRMT5-methylome in different cell types or tissues may shed light on its specific function in many other cancer types and guide the precise design of therapeutic interventions." (PMID 35803962, 2022).
cancer (continued). "Indeed, preclinical studies have shown the potential for pharmacologic inhibition of PRMT5 in the treatment of cancer." (PMID 35531958, 2022). "Numerous animal studies have suggested that the dysregulation of H4R3sme2 through downregulation of the PRMT5 protein level modifies the expression of target genes essential in cancer survival and can selectively diversify the proteome via alternative splicing." (PMID 35409411, 2022). "In cancer, PRMT5 is known to interact with cancer-associated deregulated pathways such as ErbB, FGF/FGFR signaling pathways and, for this reason, is considered a promising therapeutic target for the treatment of cancer." (PMID 39086963, 2022). "In recent years, abundant research evidence has shown that PRMT5, as an oncogene, can play an indispensable regulatory role in the pathological progression of various human cancers by promoting the proliferation, invasion, and metastasis of cancer cells." (PMID 34149432, 2021). "It has been proposed that depletion of PRMT5 may be useful for cancer therapy; however, it is cautioned that PRMT5-dependent SAMe is required for proper mRNA splicing." (PMID 34526971, 2021). "PRMT5 generates most SDMA in mammals and has been implicated in the pathogenesis of many cancers." (PMID 33440687, 2021). "PRMT5 acts as a transcriptional repressor by suppressing the expression of tumor suppressor genes and the dysregulation of PRMT5 has been reported in multiple cancer types." (PMID 34200178, 2021). "Indeed, Prmt5 function has been shown to be generally due to its enzymatic activity, and since it is upregulated in many types of cancers, it constitutes a promising therapeutic target." (PMID 34153034, 2021). "Therefore, MTA accumulation due to MTA phosphorylase (MTAP) deletion has been proposed as a vulnerability for PRMT5-targeted therapy in cancer." (PMID 34244484, 2021). "Targeting PRMT5 in cancer patients with inhibitors may also result in other side effects, such as myelosuppression." (PMID 35111150, 2021). "In addition, PRMT5 has been shown to be overexpressed in many different cancers including gastric, colorectal, lung, lymphoma, ovarian, melanoma, and glioblastoma." (PMID 33768972, 2021). "Thus, PRMT5 inhibitors can be useful for treating cancer in mono- or combination therapy with DNA-damaging agents." (PMID 34006904, 2021). "Finally, it is worth mentioning that Prmt5 has been proposed as a therapeutic target in many diseases, including cancer." (PMID 34153034, 2021). "Accumulating evidence indicates that PRMT5 promotes cancer development and progression." (PMID 33675123, 2021). "In summary, our study revealed that PRMT5 inhibitors represent a double-edged sword as they can selectively kill cancer cells but may also deter the antitumor immune response." (PMID 35111150, 2021). "PRMT5 has recently emerged as an attractive drug target for cancer therapies." (PMID 34103528, 2021). "Furthermore, GSK and the Guccione lab have shown that PRMT5 and PRMT1 inhibitors function synergistically to target MTAP-null cancer cells and tumors that are driven by splicing mutations." (PMID 33768972, 2021). "Indeed, while Cyclin D1 has been shown to be suppressed by PRMT5 inhibition in cancer cells, Cyclin D1 was unaffected by PRMT5 inhibitor treatment in untransformed Th cells, even though it is induced upon TCR stimulation." (PMID 34168658, 2021). "Increased PRMT5 expression could epigenetically modify histone (H3R8me2s and H4R3me2s) methylation and promote the transcription of gene expression, resulting in cancer progression." (PMID 33670008, 2021). "In human cancers, PRMT5 is a known driver of malignant transformation and oncogenesis." (PMID 33989303, 2021).
cancer (continued). "Inhibition of PRMT5 in pre-clinical models can lead to cancer growth inhibition." (PMID 34680285, 2021). "In cancer, RNA splicing is often dysregulated including by mutations in RNA splicing factors (RNA-SF), and inhibition of Type I PRMT and PRMT5 by MS023 and GSK591, respectively, has been shown to effectively target cells bearing RNA-SF mutations, both in vitro and in vivo." (PMID 33404912, 2021). "Prmt5 has been proposed as a therapeutic target in many diseases, including cancer." (PMID 34153034, 2021). "MTDIA therapy could therefore specifically enhance the sensitivity of cancer cells to PRMT5 or MAT2A inhibitors." (PMID 33893330, 2021). "Drugs that potently inhibit PRMT5 but have a lesser effect on immune T cell responses would be beneficial for cancer treatment while drugs that influence T cell responses may be beneficial in autoimmune and other T cell mediated diseases." (PMID 34168658, 2021). "There is much less information of PRMT5 and Cyclin E1, which may be due to the higher prevalence of cancers with Cyclin D1 than with Cyclin E1 overexpression." (PMID 34168658, 2021). "To investigate whether the effect of PRMT5 is observed in other types of cancers, we collected a series of carcinoma samples from patients." (PMID 33953349, 2021). "Importantly, this pathway can be tempered with small-molecule inhibitors that target PRMT5, offering a therapeutic node for cancer, such as HCC, that display high PRMT5–SND1 axis activity." (PMID 33768972, 2021). "Furthermore, the use of most PRMT5 inhibitors is almost exclusively focused on the treatment of cancers, and in almost all cases, the mode of inhibition is direct." (PMID 34685445, 2021). "Arginine methyltransferase 5 (PRMT5) is involved in a variety of cancers." (PMID 32392182, 2020). "Interestingly, recent studies have provided a rational combinatorial inhibition strategy of type I PRMTs and PRMT5 for synergistic killing of cancer cells." (PMID 32415090, 2020). "As Hsp90A is a known cancer-related chaperone, targeting PRMT5 may have additional anticancer benefit in lifting a protection exerted by Hsp90A over a number of oncoproteins." (PMID 32932854, 2020). "Along these lines, PRMT5 plays an important role in embryonic stem and tissue specific stem/precursor cells, and correspondingly, PRMT5 contributes to self-renewal of cancer stem cells (CSCs)." (PMID 32743345, 2020). "Here, we review current understanding of PRMT5, highlighting its role in cancer." (PMID 32743345, 2020). "Collectively, these data support the notion that phosphorylation of PRMT5 at S15 can augment NF-ĸB signaling via regulation of p65 transactivation potential and a subset of NF-κB target genes whose functions are pro-inflammatory and cancer-related in nature." (PMID 32456215, 2020). "This could present a problem if PRMT5 inhibitors are used for cancer therapy; the suppression of PRMT5 in Treg cells may augment anti-tumor responses, but the effector T cells will also be inhibited by loss of PRMT5 activity." (PMID 32328070, 2020). "siRNA-mediated PRMT5 or MEP50 knockdown inhibits anchorage-independent cancer cell proliferation." (PMID 32859041, 2020). "In addition, the local expression of key pathway enzymes (ARG1, ARG2, DDAH1, DDAH2, NOS2, ODC1, PRMT1, and PRMT5), as potential therapeutic targets, was evaluated in reference to cancer pathology." (PMID 32872669, 2020). "Considering that the MTAP gene is frequently codeleted with the adjacent cyclin‐dependent kinase inhibitor 2A (CDKN2A) locus in MM, we assessed whether PRMT5 could represent a therapeutic target also for this cancer type." (PMID 32301278, 2020). "Interestingly, we further revealed that the novel NF-κB activator—PRMT5—is also subjected to phosphorylation, which can modulate its activity to promote different types of cancers." (PMID 33375283, 2020). "PRMT5 is a ubiquitous and evolutionarily conserved protein, but it may be involved in proliferation, migration, and invasion of cancer." (PMID 32392182, 2020).
cancer (continued). "The intrinsic roles of PRMT5 in cancer could be marked by altered expression of PRMT5 or of its adaptor proteins or by altered availability of factors that control its catalytic activity." (PMID 32743345, 2020). "Emerging evidence suggests that disruption of splicing fidelity by PRMT5 depletion/inhibition could have an anti-cancer effect." (PMID 32743345, 2020). "Collectively, we have identified a novel PKCι/PRMT5/NF-κB signaling axis, suggesting that pharmacological disruption of this pivotal axis could serve as the basis for new anti-cancer therapeutics." (PMID 32456215, 2020). "Given the methyltransferase activity of PRMT5 on NF-κB activation, there is a possibility that the differential phosphorylation marks on PRMT5 may affect the tumor-promoting function of NF-κB in cancers." (PMID 33375283, 2020). "PRMT5 is overexpressed in many cancers and correlates with patient survival." (PMID 32276408, 2020). "Therefore, overexpression of PRMT5 would be a remarkable biomarker of poor prognosis and a good target for cancer treatment." (PMID 32759981, 2020). "Here, we discuss PRMT5 function in the context of cancer-related activities." (PMID 32743345, 2020). "Both PRMT1 and PRMT5 support tumor growth and are, therefore, overexpressed in a number of cancers." (PMID 32872669, 2020). "Given the pivotal roles of CSCs in drug-resistance and relapse, PRMT5 inhibition may provide a novel therapeutic modality for cancer-initiating cells." (PMID 32743345, 2020). "PRMT5 has long been known as an epigenetic modifier and regulator of gene expression and has a well-established role in development, hematopoiesis, and cancer." (PMID 30941147, 2019). "Some clues into drivers and mechanisms regulating PRMT5 protein expression may be extrapolated from cancer cells and models, in which PRMT5 protein is generally induced and contributes to tumorigenicity." (PMID 30941147, 2019). "Our present results suggest that MEP50/PRMT5 might function in cancer cell proliferation and invasion at least in part via activation of GLI1." (PMID 30675521, 2019). "Out of these, NF-κB has been shown to promote PRMT5 in cancer cells." (PMID 30941147, 2019). "PRMT5 is a key and emerging stemness factor for normal and cancer stem cells." (PMID 31694585, 2019). "In addition, we observed that exposure of cancer cells to LPS triggers protein arginine methyltransferase 5 (PRMT5)-mediated monomethylation of arginine 50 in ENO-1 and thus enhances cell surface expression of this protein." (PMID 31106201, 2019). "It would be of interest to understand the mechanisms involved in PRMT5 regulation in the nucleus of tumoral cells and to investigate whether its dual prognostic value can be extended to other cancers." (PMID 31139329, 2019). "Accumulating evidence suggests that PRMT5 may function as an oncogene to drive cancer cell growth and metastasis by epigenetically silencing several tumor suppressor genes." (PMID 30922330, 2019). "Therefore, targeting PRMT5 coupled with targeted therapy represents a rational strategy for both cancer immunotherapy and tumor-targeted therapy." (PMID 30800128, 2019). "The role of PRMT5 in cancer has received increasing attention recently." (PMID 30922330, 2019). "Programmed Cell Death 4 (PDCD4) is a tumor suppressor protein whose expression has been shown to correlate with better survival in various cancers; however, upon interaction with PRMT5, PDCD4 becomes methylated at R110 and loses its tumor suppressor activity in MCF-7 cells." (PMID 30613353, 2018). "Our data suggest that cancer cells treated with PRMT5 inhibitors exhibit defects in cellular splicing early, followed up by significant changes in gene expression, highlighting the splicing phenotype as an early event in the response to PRMT5 inhibition." (PMID 29946150, 2018).